Y_RNA (Y RNA )
Gene: Miscellaneous RNA gene on chromosome 22 (41,045,497 to 41,045,591, forward strand). Ensembl gene ENSG00000222698.
Homologues: Orthologues: chimpanzee Y_RNA (98% identical), macaque Y_RNA (88% identical). Paralogues in human: RNY4P10 (82% identical), Y_RNA (82% identical), RNY4 (81% identical), RNY4P19 (81% identical), RNY4P14 (80% identical), RNY4P25 (80% identical), RNY4P27 (80% identical), Y_RNA (80% identical), RNY4P37 (79% identical), RNY4P6 (79% identical), RNY4P7 (79% identical), RNY4P9 (79% identical), and 89 more.